IL24 (interleukin 24)
Diseases named in the same sentence as IL24 in open-access papers (continued):
Sharing a sentence is not in itself a finding about the gene and the disease.
melanoma (continued). "In oral cancer cells, miR-205-5p has been found to promote IL-24 expression, whereas in melanoma cells, miR-205-5p has been found to inhibit CCL18 release via targeting its 3’UTR." (PMID 36435866, 2022). "It was reported that IL-24 expression during terminal differentiation in human melanoma cells is regulated predominantly at a posttranscriptional level." (PMID 36282328, 2022). "IL-24 exhibits its anti-tumor activity in a broad spectrum of cancers including melanoma through inhibition of PI3K, EGFR, and PKR induction in breast and NSCLC." (PMID 33918490, 2021). "IL-20 and IL-26 were discovered to promote proliferation and migration of bladder cancer, breast cancer, and gastric cancer cells, while IL-24 was found to inhibit the proliferation and metastasis of melanoma, prostate cancer, and OC." (PMID 34114949, 2021). "Erlotinib was also combined to interleukin 24 (IL-24) based on the later expression in normal melanocytes, monocytes, and in early stages of melanoma, but was lost during progression." (PMID 33918490, 2021). "The combination effect of MDA-7/IL-24 with temozolomide, an alkylating agent, was investigated in human melanoma and glioma cells." (PMID 35008495, 2021). "Protein expression of MDA-7/IL-24 is decreased during progression from melanocyte to melanoma and remains undetectable in metastatic melanoma lending to its classification as a putative tumor suppressor." (PMID 35008495, 2021). "Our results also confirmed up-regulation of Bax and caspase-3 and down-regulation of Bcl-2 in melanoma of mouse models after administration of IL-24-iMSCs, demonstrating that IL-24 contributed to the anti-tumor effects of IL-24-iMSCs." (PMID 32015693, 2020). "Interleukin-24 (IL-24) is a therapeutic gene for melanoma, which can induce melanoma cell apoptosis." (PMID 32015693, 2020). "In the present study, CM-DIL labeled iMSCs and IL-24-iMSCs were found in established melanoma of mouse models after retro-orbital injection, indicating that MSCs derived from iPSCs can also be recruited to the site of the tumor." (PMID 32015693, 2020). "Of note, some of these cytokines are known activators of STAT3 signaling (IL-8, IL-1β and IL-24), which is protumorigenic and favors melanoma reprogramming towards a tumor-initiating phenotype." (PMID 31906480, 2020). "IL-24-iMSCs were transplanted into the melanoma-bearing mice by retro-orbital intravenous injection." (PMID 32015693, 2020). "Histological analysis of melanoma tissue sections indicated that there were necrotic areas and nuclear agglomeration areas in the tumors in IL-24-iMSCs group and iMSCs group." (PMID 32015693, 2020). "IL-24-iMSCs exerted a significant inhibitory effect on the growth of melanoma in subcutaneous mouse models, in which the migration of IL-24-iMSCs to tumor tissue was confirmed." (PMID 32015693, 2020). "Our previous data showed that MSCs derived from human iPSCs with the integration of IL-24 (IL-24-iPSCs) significantly inhibited the growth of melanoma cell when co-implanted into mice." (PMID 32015693, 2020). "Independently of its cognate receptors, adenovirus-mediated IL-24 overexpression in melanoma cells led to induction of apoptosis by interaction with glucose-regulated protein 78 (GRP78) and upregulation of GADD family genes, including CHOP18,19." (PMID 31907348, 2020). "The inhibitory effect of IL-24-iMSCs on the melanoma cells was investigated in a co-culture system and tumor-bearing mice." (PMID 32015693, 2020). "Our results demonstrated that IL-24-iMSCs significantly inhibited the growth of melanoma in tumor-bearing mice after systemic administration." (PMID 32015693, 2020).
melanoma (continued). "The expression level of IL-24 in IL-24-iMSCs reached 95.39 ng/106 cells/24 h, which is significantly higher than that in iMSCs, inducing melanoma cells apoptosis more effectively in vitro compared with iMSCs." (PMID 32015693, 2020). "Interleukin 24 (IL-24) is originally produced in human melanoma tumor cells and exhibits anti-tumor effect by enhancing cancer cell apoptosis, inhibiting cancer metastasis, and improving immune regulation." (PMID 32318337, 2020). "MSCs derived from iPSCs with the integration of IL-24 at rDNA locus can inhibit the growth of melanoma in tumor-bearing mouse models when administrated via retro-orbital injection." (PMID 32015693, 2020). "In the present study, we differentiated IL-24-iPSCs to IL-24-iMSCs and investigated the anti-melanoma effect of IL-24-iMSCs on established tumor after retro-orbital injection into a tumor-bearing mouse model." (PMID 32015693, 2020). "The growth curve of melanoma revealed that both IL-24-iMSCs and iMSCs inhibited the growth of B16-F10." (PMID 32015693, 2020). "IL24/MDA‐7, originally identified as a gene whose expression is induced during melanoma differentiation, inhibits tumour growth in different contexts." (PMID 31081251, 2019). "EL-4-LX/IL-24 immunization cannot inhibit B16 melanoma growth as compared to the B16 group, suggesting that the therapeutic effect of LX/IL-24-modified tumor cells was specific to autologous tumor." (PMID 31338417, 2019). "The cytotoxicity assay showed that LX/IL-24-infected murine melanoma cells significantly enhanced the antitumor immune response in vitro." (PMID 31338417, 2019). "In another work, adenoviral transduction was used to express both melanoma differentiation-associated gene-7 (MDA-7) and interleukin-24 (IL-24), two known inducers of apoptosis by ROS increase, in different cancer cell lines." (PMID 31097977, 2019). "Now, we demonstrate for the first time that IL-24 inhibits eIF4A expression in prostate cancer cells (DU-145), melanoma (HO-1), breast cancer cells (MCF-7), and cervical cancer cells (HeLa)." (PMID 29786657, 2018). "There is increasing evidence that IL24 inhibits growth of many diverse human cancers including melanomas, breast cancer, pancreatic cancer, gliomas, hepatocellular cancers and ovarian cancer without adversely affecting normal cells or tissues." (PMID 28388559, 2017). "Immunofluorescence analysis of the tumors revealed that CM-Dil-positive IL24-iMSCs expressed human IL24 in the mouse melanomas." (PMID 28388559, 2017). "In vivo tumor xenograft studies in mice demonstrated that IL24-iMSCs inhibited melanoma growth more than control iMSCs did." (PMID 28388559, 2017). "Many studies demonstrated that IL24, a cytokine of the IL-10 family that was originally identified from metastatic human melanoma cells, induced cancer cell apoptosis." (PMID 28388559, 2017). "Functionally, IL24-iMSCs induced in vitro apoptosis in B16-F10 melanoma cells more efficiently than control iMSCs when co-cultured in Transwell assays." (PMID 28388559, 2017). "Our studies demonstrated therapeutic efficacy of MSCs derived from the transformed iPSCs (with IL24 gene) in a mouse melanoma model." (PMID 28388559, 2017). "Then, we determined if the IL24-iMSCs efficiently induced in vitro melanoma cell apoptosis by co-culturing IL24-iMSCs and B16-F10, a mouse melanoma cell line in a transwell system." (PMID 28388559, 2017). "Studies have shown that loss of IL-24 expression correlated with disease progression in melanoma and lung cancer, indicating a tumor suppressive role for IL-24." (PMID 27602961, 2016). "Analysis of IL-24 mRNA expression in 4 melanoma cell lines (A375, SK-MEL23, SK-MEL30, SK-MEL28) and primary melanocytes revealed a reduction in expression." (PMID 27387763, 2016). "It is also reported that IL-24 induces apoptosis in melanoma cells, and enhances antitumor activities when applied in combination with paclitaxel in breast and prostate cancers." (PMID 26528857, 2015).
melanoma (continued). "As a novel candidate for cancer gene therapy, IL-24 was cloned using subtraction hybridization from terminally differentiated human melanoma cells." (PMID 26361755, 2015). "We further tested IL-24 protein expression in a human melanoma (MeWo) cell line and compared to protein expression in H1299 cells by transient transfection using the pcDNA3.1-IL24wt or -IL24mt plasmids." (PMID 26009991, 2015). "The protein expression of MDA-7/IL-24 is decreased during melanoma progression, with almost imperceptible levels in metastatic disease." (PMID 24527085, 2014). "Immunohistochemical analysis of melanocytes, nevi and in different stages of melanoma showed IL-24 protein expression progressively decreased with disease progression from primary to metastatic phase with complete loss of expression in the metastatic phase." (PMID 24377906, 2013). "The IL-24 gene was originally discovered by subtraction hybridization method by exposing human melanoma cells (HO1 cell line) to the terminal differentiation inducing agents such as IFN-beta (IFN-β) and mezerin." (PMID 24377906, 2013). "In melanoma cells, p38MAPK signaling was demonstrated to be important for IL-24-mediated tumor cell killing." (PMID 24377906, 2013). "Treatment of human pancreatic tumor cells and melanoma cells with human IL-24 protein produced in eukaryotic cells exhibited potent cytotoxicity." (PMID 24377906, 2013). "Inhibiting p38MAPK with SB203580, a specific small molecule inhibitor abrogated IL-24-induced melanoma apoptosis." (PMID 24377906, 2013). "MDA-7/IL-24 expression in melanoma negatively correlates with inducible nitric oxide synthase (iNOS) expression." (PMID 22629368, 2012). "Located on chromosome 1q32, the anti-tumor effects of MDA-7/IL-24 have been validated on cancer cell lines that include melanoma, breast cancer, prostate cancer, hepatocellular carcinoma, GBM and others." (PMID 22808125, 2012). "The present findings revealed that MDA-7/IL-24 treatment of melanoma cells activates phosphorylation of STAT3 and down-regulates interferon regulatory factor (IRF-1) whereas up-regulating IRF-2 expression, which reduces iNOS expression level." (PMID 22629368, 2012). "MDA-7/IL-24 induces growth suppression and apoptosis in a broad spectrum of human cancer cells, including melanoma, malignant glioma, and carcinomas of the breast." (PMID 22629368, 2012). "MDA-7/IL-24, although initially found to be up-regulated in melanoma cells, has been shown to have a growth inhibitory role in certain cancer cells which include ovarian, colorectal and glioma cancer cells." (PMID 21524313, 2011). "IL-24 was originally identified as mda-7, a gene selectively up-regulated during terminal differentiation of melanoma cells and later classified as a member of the IL-10 family." (PMID 20137089, 2010). "Melanoma differentiation associated gene-7 (MDA-7), also known as interleukin (IL)-24, is a tumour suppressor gene associated with differentiation, growth and apoptosis." (PMID 20735832, 2010). "Other studies demonstrated that IFN-β or IL-24 down-regulated the DNA repair enzyme O6-methylguanine-DNA methyltransferase expression and activity in neuroblastoma and melanoma, respectively." (PMID 20178622, 2010). "IL-24 expression can be detected in melanocytes and early melanomas but expression levels decrease as melanomas advance becoming virtually undetectable in metastatic disease." (PMID 20072629, 2010). "On the other hand, studies in melanoma cells and PBMCs have suggested, that post-transcriptional gene regulation by mRNA stabilization is of major importance to IL-24 gene expression." (PMID 20072629, 2010). "Melanoma differentiation associated gene-7 (MDA-7), also known as interleukin (IL)-24, is an intriguing member of the class II/IL-10 cytokine family." (PMID 20735832, 2010).
melanoma (continued). "IL-24-induced p38 MAPK activation promoted survival of chronic lymphocytic leukaemia B-cells whereas ad.mda-7-induced p38 MAPK activation in melanoma cells lead to apoptosis." (PMID 20072629, 2010). "In view of this, care should be taken when attributing the cytokine IL-24 itself with apoptosis-inducing properties on melanoma cells." (PMID 18074024, 2007). "Initial evidence on IL-24-induced apoptosis of cancer cells came from Paul Fisher's group who showed that transient transfection of IL-24 into melanoma cells reduced colony numbers while healthy cells remained unaffected by such a paradigm." (PMID 18074024, 2007). "Relative to primary NHEM cells, only 3 melanoma cell lines were found to express IL-24 (A375, IPC298, and Wm9)." (PMID 18074024, 2007). "Focusing on IL-24, we then performed standard dose-response and extended kinetic studies on HaCaT keratinocytes and the two melanoma cell lines MeWo and Wm35." (PMID 18074024, 2007). "Previous reports have suggested that melanoma cells express receptors for IL-24 although it is unclear how this was analysed." (PMID 18074024, 2007). "Focusing on melanoma cells and on the “cytokine-like” properties of IL-24, we first stimulated a panel of 14 different cell lines with commercially available recombinant IL-24." (PMID 18074024, 2007). "This contrasts with previous reports where IL-24 was shown to disappear with progression of melanoma in primary patient samples." (PMID 18074024, 2007). "Additionally, we constructed IL-24-silenced luci-A375 cells and co-incubated them with Vin and PBMCs to assess PBMC-mediated cytotoxicity against the IL-24-silenced melanoma cells." (PMID 40866941, 2025). "Furthermore, M7S in combination with immune checkpoint inhibitors, specifically anti‐PD‐L1, led to more robust tumor suppression in syngeneic melanoma models than the combination with IL‐24." (PMID 40338095, 2025). "Accumulating evidence from experimental and clinical datasets consistently demonstrates decreased IL‐24 levels in lung, colorectal, pancreatic, endometrial, head and neck, ovarian cancers, melanoma, and glioblastoma, with no discernible impact on normal cells." (PMID 40338095, 2025). "The anti-tumor efficacy of Vin or IL-24 in combination with PD-1 monoclonal antibody, as well as their modulation of the tumor microenvironment, were validated through luciferase-mediated cytotoxicity assays and a murine melanoma model." (PMID 40866941, 2025). "assessed the functionality of glycosylated secreted IL‐24 in melanoma cell lines." (PMID 40338095, 2025). "Given the increased IL-24 secretion by Vin-treated melanoma cells, we hypothesized that Vin enhances CD8+ T cell function through IL-24 secretion from melanoma cells." (PMID 40866941, 2025). "Together, these results indicate that ATF3 may act as a key transcriptional regulator linking P38 activation to IL-24 upregulation, thereby contributing to the anti-melanoma effects of Vin." (PMID 40866941, 2025). "This decline in IL-24 expression appears to coincide with the progression of melanoma." (PMID 40806452, 2025). "Moreover, it activates the P38/MAPK/ATF3 signaling pathway to stimulate IL-24 secretion by melanoma cells, which contributes to reshaping the immunosuppressive TME and enhancing CD8+ T cell-mediated immune responses." (PMID 40866941, 2025). "Thus, upregulation of IL24 expression in melanoma cells was a consequence of induction of lethal levels of ER‐stress." (PMID 38414326, 2024). "Melanoma sensitivity to PIKFYVE inhibitors was related directly to IL24 expression." (PMID 38414326, 2024). "Thus, unlike thapsigargin and tunicamycin, which induce ER‐stress indiscriminately, PIKFYVE inhibitors selectively terminated PIKFYVE‐sensitive melanoma by inducing IL24‐dependent ER‐stress." (PMID 38414326, 2024).
melanoma (continued). "IL24 expression was also upregulated by either thapsigargin or tunicamycin, drugs that induce a lethal ER‐stress response by totally different mechanisms, thereby confirming that IL24 dependent termination of autophagy‐dependent melanoma results from induction of ER‐stress." (PMID 38414326, 2024). "Ectopically expressed interleukin-24 amplifies the ability of WX8 to kill melanoma cells." (PMID 38994949, 2024). "However, suppression of IL24 expression with siRNA only marginally reduced proliferation of either melanoma A375 cells or HFF1 foreskin fibroblasts." (PMID 38414326, 2024). "Thus, melanoma cells that produce high levels of IL24 are most likely to be sensitive to PIKFYVE inhibition." (PMID 38414326, 2024). "Therefore, even a 90% reduction in the endogenous level of endogenous IL24 protein would have little effect on melanoma viability." (PMID 38414326, 2024). "It was reported that NaBu was able to induce the endongous IL-24 mRNA expression level in human malignant melanoma cell line A375, therefore, we treated adapted FCHO/IL-24 cells with various concentrations of NaBu under different culture conditions to further optimize rhIL-24 production." (PMID 36282328, 2022). "Additionally, combinatorial therapy using MDA-7 (IL-24) or M7S (IL-24S) with an immune checkpoint inhibitor, anti-PD-L1, dramatically reduced tumor progression in murine B16 melanoma cells." (PMID 35402258, 2022). "MDA-7/IL-24 selectively induces apoptosis and/or toxic autophagy in a broad spectrum of cancer cell types, including breast cancer, prostate cancer, melanoma, glioblastoma multiforme, neuroblastoma, lung, and numerous other cancers." (PMID 33670594, 2021). "Importantly, Immunofluorescence analysis demonstrates that both CM-Dil-labeled IL-24-iMSCs with the expression of IL-24 and iMSCs exist in melanoma of the treated group." (PMID 32015693, 2020). "This study aims to investigate whether MSCs derived from the iPSCs with the site-specific integration of IL-24 can inhibit the growth of melanoma in a tumor-bearing mouse model via retro-orbital injection." (PMID 32015693, 2020). "To investigate whether IL-24-iMSCs can induce apoptosis in melanoma cells in vitro, we co-cultured mouse melanoma cells (B16-F10) with IL-24-iMSCs, or with iMSCs, followed by incubated with Annexin V-FITC and PI antibody." (PMID 32015693, 2020). "We found that IL-24-iMSCs could inhibit the growth of melanoma in tumor-bearing mice more significantly, which was related to the anti-tumor effect of IL-24." (PMID 32015693, 2020). "Interleukin-24/Melanoma differentiation-related gene-7 (MDA-7/IL-24) is a new member of the IL-10-associated cytokine gene family, and the IL-24 gene encodes a 206-amino acid precursor protein that contains a 48-amino acid signal sequence and a mature fragment of 158 amino acids." (PMID 32015693, 2020). "Furthermore, both IL24-iMSCs and iMSCs induced apoptosis in melanoma cells, thereby inhibiting melanoma growth in vivo." (PMID 28388559, 2017). "Overexpression of IL24 selectively inhibits the growth of melanoma cells and induces apoptosis." (PMID 28388559, 2017). "MDA-7/IL-24 acts as a growth suppressor in melanoma and other cancer cells." (PMID 27931220, 2016). "Interestingly, IL24/mda-7 is classified as a tumor suppressor in several cancers including: melanoma, gall bladder and lung." (PMID 26498364, 2015). "For example, combination of oncolytic adenovirus expressing IL-24 with chemotherapeutic agents dramatically enhanced the cytotoxic effects through induction of apoptosis against cancer of the breast, colon, liver, lung, brain, pancreas, and melanoma." (PMID 24377906, 2013). "Similarly, treatment of melanoma cells with Ad-IL24 plus Temozolomide produced greater antitumor activity." (PMID 24377906, 2013).